RFXANK (regulatory factor X associated ankyrin containing protein)
Description:
Activates transcription from class II MHC promoters. Activation requires the activity of the MHC class II transactivator/CIITA. May regulate other genes in the cell. RFX binds the X1 box of MHC-II promoters. May also potentiate the activation of RAF1 (By similarity). Isoform 2 is not involved in the positive regulation of MHC class II genes.
Synonyms: RFX-B; ANKRA1; BLS; F14150_1; MGC138628; MHC2D2
Tractability: PROTAC: ubiquitination databases record sites on it.
Gene: Protein-coding gene on chromosome 19 (19,191,957 to 19,202,844, forward strand). Ensembl gene ENSG00000064490.
Subcellular location: Cytoplasm; Nucleus
Subcellular location (Human Protein Atlas): Nucleoplasm
Gene Ontology:
Molecular function: DNA-binding transcription activator activity, RNA polymerase II-specific; protein binding; RNA polymerase II transcription regulatory region sequence-specific DNA binding; histone deacetylase binding
Biological process: positive regulation of transcription by RNA polymerase II; positive regulation of MHC class II biosynthetic process
Cellular component: nucleoplasm; nucleus; RNA polymerase II transcription regulator complex; cytoplasm
Genetic constraint (gnomAD): Loss-of-function variants: 20 observed, 35.83 expected, observed/expected ratio (o/e) 0.56, 90% interval 0.39 to 0.81. The upper end of that interval is the gene's LOEUF score, 0.81, which puts it in group 3 of 6, group 1 being the genes least tolerant of losing a copy. Missense variants: 295 observed, 359.08 expected, observed/expected ratio (o/e) 0.82, 90% interval 0.75 to 0.9. Synonymous variants: 154 observed, 156.72 expected, observed/expected ratio (o/e) 0.98, 90% interval 0.86 to 1.12.
Gene-disease validity (ClinGen):
ClinGen rates the evidence that RFXANK causes each of these diseases.
MHC class II deficiency (autosomal recessive): Definitive.
Homologues: Orthologues: chimpanzee RFXANK (99% identical), dog RFXANK (93% identical), pig RFXANK (92% identical), guinea pig RFXANK (87% identical), mouse Rfxank (85% identical), rat Rfxank (82% identical), macaque RFXANK (74% identical), tropical clawed frog rfxank (64% identical), zebrafish rfxank (52% identical). Paralogues in human: ANKRA2 (53% identical), NFKBID (23% identical), NFKBIZ (22% identical).
Diseases named in the same sentence as RFXANK in open-access papers:
RFXANK is named in the same sentence as 27 diseases in open-access papers, as found by Europe PMC text mining. Sharing a sentence is not in itself a finding about the gene and the disease. The quoted sentences say what the papers report.
bare lymphocyte syndrome (8 papers, 2012 to 2025). "This is the first report of CIITA deficiency in Morocco, and the variant itself is reported here for the first time worldwide, expanding the genetic spectrum of bare lymphocyte syndrome beyond the well-known North African founder mutation in RFXANK." (PMID 41376631, 2025). "The second case concerned a 16-month-old boy who also carried two variations, a heterozygous nonsense nucleotide substitution mutation in the NOD2 gene, and a homozygous nucleotide deletion mutation in the RFXANK gene, responsible of Blau syndrome and MHC class II deficiency, respectively." (PMID 35529857, 2022). "Major histocompatibility complex class II (MHC II) deficiency (bare lymphocyte syndrome type II) is an autosomal-recessive combined immunodeficiency caused by pathogenic variants in the transcriptional regulators CIITA, RFXANK, RFX5, or RFXAP." (PMID 41376631, 2025). "Five children (13.9%) were identified with a defect in MHC class II expression—bare lymphocyte syndrome (BLS), and this was accounted for by variants in CIITA (n = 3), RFXANK (n = 1), and RFX5 (n = 1)." (PMID 33519828, 2020). "Mutations in CIITA or any of the four RFX regulatory genes (RFXANK, RFX5, and RFXAP) cause bare lymphocyte syndrome type II (BLSII), an immunodeficiency characterized by the lack of MHC class II expression." (PMID 32375397, 2020).
combined immunodeficiency (4 papers, 2012 to 2025). A broad classification of inherited disorders presenting at birth that affect both the cell-mediated and humoral aspects of the immune response. "The mortality rate was the highest in patients with non-syndromic combined immunodeficiency (51.7%, median age: 3.5 years) and particularly in patients with mutations in specific genes associated with this phenotype (RFXANK, RAG1, and IL2RG)." (PMID 34052995, 2021). "Genetic studies of patients with combined immunodeficiency (CID) with predominant CD4 cell deficiency have revealed mutations in genes encoding regulatory factors of the expression of MHC class II molecules such as CIITA, RFXANK, RFX5 or RFXAP." (PMID 25205547, 2014).
immunodeficiencies (3 papers, 2021 to 2025). "RFXANK mutations are prevalent in bare lymphocyte syndrome (BLS) group B, an immunodeficiency disorder affecting CD4+ T and B cells." (PMID 37040172, 2023). "For example, in subclusters of osteo-like, basal/stromal, and endothelial cells, regulatory factor X (RFX5, RFXAP, and RFXANK) can mediate their immunodeficiency function by binding domains of RFX- and NFX-." (PMID 35237614, 2021). "The MENA registry also reported high mortality in non-syndromic combined immunodeficiencies (51.7%) and syndromic CID (22.5%), particularly in patients with RFXANK, RAG1, and IL2RG mutations, where the most common causes of death were infection and respiratory failure." (PMID 40806973, 2025).
acute myeloid leukemia (1 paper, 2018). Acute myeloid leukemia (AML) is a group of neoplasms arising from precursor cells committed to the myeloid cell-line differentiation. "Finally, it was observed that the caspase-2-RFXANK interaction occurred in the cytoplasmic compartment, as verified by co-IP of endogenous caspase-2 using a specific RFXANK antibody and fractionated acute myeloid leukemia OCI-AML2 cell lysates." (PMID 29362422, 2018).
congenital adrenal hyperplasia (1 paper, 2022). Congenital adrenal hyperplasia (CAH) is an inherited endocrine disorder caused by a steroidogenic enzyme deficiency that is characterized by adrenal insufficiency and variable degrees of hyper or hypo androgyny manifestations, depending of the type and the severity of the disease. "Finally, a patient was diagnosed with two homozygous pathogenic variants: one causing congenital adrenal hyperplasia (non- IEI) and the other in RFXANK gene causing MHCII deficiency." (PMID 35482138, 2022).
COVID-19 (1 paper, 2023). A disease caused by infection with severe acute respiratory syndrome coronavirus 2. "When analyzing the DEGs using the bioinformatic platform Enrichr-KG, the most relevant transcription factors potentially driving the differences in kidney gene expression between COVID-19 AKI and non-COVID-19 AKI were POLR2L, EIF3K, BOLA3, RFXANK, and ZNF576." (PMID 38003268, 2023).
deficiencies (1 paper, 2025). "Among these factors, mutations in RFXANK account for 70% of MHC-II deficiencies, with 19 mutations identified to date." (PMID 40756102, 2025).
gastrointestinal infections (1 paper, 2022). "Individuals with biallelic variants in the RFXANK gene have early onset and severe recurrent respiratory and gastrointestinal infections." (PMID 36085161, 2022).
lymphopenia (1 paper, 2019). Reduction in the number of lymphocytes. "Isolated CD4 lymphopenia has been described with MHC Class II deficiency (RFXANK, CIITA, RFXAP) and hypomorphic RAG variants." (PMID 31572360, 2019).
nasopharyngeal carcinoma (1 paper, 2022). A carcinoma arising from the nasopharyngeal epithelium. "RFXANK mutations were reported to be associated with stomach cancer and nasopharyngeal carcinoma." (PMID 35227285, 2022).
Obesity (1 paper, 2023). Accumulation of substantial excess body fat. "However, RFXANK has not been associated with obesity or T2D in previous studies, though MHCII has been found to play a role in obesity, and our own prior studies have identified pathways related to inflammation and immunity as common themes in individuals at risk for T2D." (PMID 37040172, 2023).
ovarian carcinoma (1 paper, 2021). A malignant neoplasm originating from the surface ovarian epithelium. "Given the up-regulated RFXANK and down-regulated CDC42EP3 and BAMBI in two independent ovarian cancer datasets from Oncomine, we expected CDC42EP3 as a potential prognostic target that needs further investigation." (PMID 34616622, 2021). "The correlations between the expression levels of RFXANK, CDC42EP3 and BAMBI and prognosis in ovarian cancer patients were analyzed by the PrognoScan database." (PMID 34616622, 2021).
primary immunodeficiency (1 paper, 2015). "RFXANK (primary immunodeficiency signaling) and CIITA (class II major histocompatibility complex transactivator involved in Antigen Presentation Pathway, Primary Immunodeficiency Signaling and TREM1 Signaling) were other high scoring molecules." (PMID 26302420, 2015).
cancer (7 papers, 2021 to 2026). A tumor composed of atypical neoplastic, often pleomorphic cells that invade other tissues. "Strikingly, we also demonstrated that the driving of TEAD4 into the condensate state by VGLL4/RFXANK or an engineered peptide significantly limited cancer cell growth and increased apoptosis." (PMID 39358623, 2024). "Other important positive biomarkers shared across all 18 cancer types were RFXANK, RFXAP, and RFX5, which form the RFX trimeric complex." (PMID 34430923, 2021). "Additionally, fifteen genes were associated with cancer control; among these, three were related to immunity (MAGT1, RFXANK and SKAP2), two (ADGRL3 and TENM3) were related to cell adhesion, and two (ADAM11 and TEP1) were found to be tumor suppressor genes." (PMID 34107880, 2021). "The regulation of these genes’ expression by RFXANK, RFXAP, and RFX5 TFs has been pointed across 18 different cancer types." (PMID 40226614, 2025). "We also identified the top 1 GEAR in individual cancer types, such as TLL1 (BLCA), PGK1 (BRCA), RFXANK (CESC), DPP7 (COAD), VWA8 (KIRC), SCMH1 (LGG), HILPDA (LIHC), TLE1 (LUAD), CD151 (LUSC), ANKRD13A (OV), SOCS2 (PAAD), DRG2 (PRAD), ADAMTS6 (STAD), PSMB8 (THCA), ASS1 (UCEC)." (PMID 41404730, 2025).
tumor (3 papers, 2021 to 2025). "Specifically, hepatocytes at the tumor periphery predominantly expressed TFs such as ILF2, ATF7, and RFXANK, while those in the tumor core were enriched for KLF4, EGR1, and HES5." (PMID 40474968, 2025). "Taken together, these results indicate that VGLL4 and RFXANK can directly induce TEAD4 LLPS both in vitro and in vivo, and these condensates may function as repressors of transcription to eventually induce tumor cell apoptosis." (PMID 39358623, 2024).
RFXANK also shares sentences with these, for which no sentence is quoted: immunity disorder (3 papers); bipolar disorder (1); Blau syndrome (1); glioblastoma (1); infection (1); lymphoid cancers (1); melanoma (1); MHC class II deficiency (1); multiple sclerosis (1); respiratory failure (1); schizophrenia (1); stomach cancer (1).